DCANP1 (dendritic cell associated nuclear protein 1)
Description:
Binds with and transactivates the corticotropin-releasing hormone (CRH) promoter.
Synonyms: C5orf20; DCNP1
Tractability: No criterion of Open Targets' tractability assessment is met for any kind of drug.
Gene: Protein-coding gene on chromosome 5 (135,444,214 to 135,447,348, reverse strand). Ensembl gene ENSG00000251380.
Subcellular location: Nucleus; Cytoplasm
Subcellular location (Human Protein Atlas): Nucleoplasm; Nuclear bodies
Gene Ontology:
Molecular function: protein binding
Biological process: auditory behavior; cochlea development; cochlea morphogenesis; craniofacial suture morphogenesis; genitalia development; genitalia morphogenesis; hard palate morphogenesis; inner ear development; inner ear morphogenesis; learned vocalization behavior; mastication; negative regulation of relaxation of muscle; negative regulation of saliva secretion; neuromuscular process controlling balance; peristalsis; regulation of muscle organ development; thorax and anterior abdomen determination; trigeminal nerve development; vestibulocochlear nerve formation
Cellular component: cytoplasm; nucleus
Genetic constraint (gnomAD): Loss-of-function variants: 1 observed, 0.13 expected, observed/expected ratio (o/e) 7.72. That is too few expected variants to judge how well the gene tolerates losing a copy. Missense variants: 328 observed, 308.03 expected, observed/expected ratio (o/e) 1.06, 90% interval 0.97 to 1.17. Synonymous variants: 139 observed, 130.26 expected, observed/expected ratio (o/e) 1.07, 90% interval 0.93 to 1.23.
Homologues: Orthologues: chimpanzee DCANP1 (93% identical).
Diseases named in the same sentence as DCANP1 in open-access papers:
DCANP1 is named in the same sentence as 3 diseases in open-access papers, as found by Europe PMC text mining. Sharing a sentence is not in itself a finding about the gene and the disease. The quoted sentences say what the papers report.
cancer (2 papers, 2024 to 2025). A tumor composed of atypical neoplastic, often pleomorphic cells that invade other tissues. "There are plenty of other potential non-coding genes that are likely cancer antigens, including HMHB1, DCANP1 and PRAC2." (PMID 39713347, 2024).
DCANP1 also shares sentences with these, for which no sentence is quoted: asthma (1 paper); depressive disorder (1).